INS (insulin)
Diseases named in the same sentence as INS in open-access papers (continued):
Sharing a sentence is not in itself a finding about the gene and the disease.
nesidioblastosis (continued). "Moreover, in cases where imaging results are inconclusive, the presence of a positive selective arterial calcium stimulation test (SACST) exhibiting a diffuse pattern and a doubling or tripling of the basal hepatic venous serum insulin concentration indicates nesidioblastosis." (PMID 38817472, 2024). "Interestingly, prolonged inhibition of TMEM219 signaling using ecto-TMEM219 treatment appeared to prevent normal beta-cell turnover and increased peripheral insulin levels to the point that the beta-cell mass markedly expanded, almost mimicking nesidioblastosis." (PMID 35115561, 2022). "Another explanation involves nesidioblastosis occurring post RYGB due to long-term stimulation of beta-cell growth by altered gut hormones, notably glucagon-like peptide 1 (GLP-1), which enhances insulin secretion and sensitivity." (PMID 38817472, 2024). "The insulin secretion persisted throughout the culture period of an infant-derived nesidioblastosis cell line, which is not the case upon a long-term passage in normal islet cells." (PMID 37371827, 2023). "Further results supported this conclusion, adding that in nesidioblastosis, this similarity is not only anatomic, but also functional, because of their defective recognition of nutrient secretagogues, and lack of glucose dependence of their cAMP mediated insulin release." (PMID 19545371, 2009).
systemic lupus erythematosus (29 papers, 2006 to 2025). An autoimmune multi-organ disease typically associated with vasculopathy and autoantibody production. "SLE patients showed a higher frequency of 14bp INS allele and 14bp INS/INS genotype and the heterozygote group showed lower systemic lupus erythematosus disease activity index (SLEDAI) indexes than homozygous groups." (PMID 25477881, 2014). "For the upregulated signaling pathways, we found that they were mainly enriched in the signaling pathways of glucose metabolism (pyruvate metabolism, insulin signaling, glycerophospholipid metabolism) and immune response (autoimmune thyroid disease and systemic lupus erythematosus)." (PMID 36945018, 2023). "For instance, CD4 + T cells in Lupus patients show epigenetic changes in the insulin pathway." (PMID 33298174, 2020). "Using a combination of immunochemical and cellular studies, we investigated the presence of anti-adipocyte autoantibodies in patients with AGL, acquired partial lipodystrophy, localized lipoatrophy due to intradermic insulin injections or systemic lupus erythematosus." (PMID 30283460, 2018). "Additionally, in an open-label trial of patients with psoriatic arthritis, pioglitazone reduced both tender and swollen joint counts, and pioglitazone decreased CRP and serum amyloid A and improved insulin sensitivity in patients with uncomplicated systemic lupus erythematosus." (PMID 24020899, 2013). "A 42-year-old female with systemic lupus erythematosus (SLE), diabetes, and hypertension on lisinopril, hydroxychloroquine, metformin, insulin, and prednisone, presents to the emergency department with right sided groin pain." (PMID 37465540, 2021).
Zinc deficiency (29 papers, 2011 to 2025). A deficiency of the essential metal Zinc; an essential cofactor for many enzymes. "The crucial role of zinc in insulin synthesis, storage, and secretion indicates that zinc deficiency can directly impair glucose homeostasis." (PMID 41141262, 2025). "The expression and activity of these transporters are influenced by various factors, including cytokines (IL-1β, IFN-γ, and IL-6), hormones (insulin), zinc deficiency, and excess zinc." (PMID 39195249, 2024). "Zinc deficiency leads to a reduction in the expression of ZnT8, ultimately impairing insulin secretion." (PMID 39195249, 2024). "Zinc deficiency has been shown to decrease the total number of insulin granules in pancreatic β-cells and to impair insulin sensitivity and glucose tolerance in obese rats and mice." (PMID 38260166, 2023). "It is also observed that in the case of zinc deficiency, insulin is less stable and degrades faster." (PMID 34203167, 2021). "Decreases in body weight, growth hormone, dietary intake, thymic organ coefficient, IL-1/IL-6, thymosin, and insulin in LZG indicated that zinc deficiency negatively affected growth, immunity, and sugar metabolism in rats." (PMID 31687040, 2019). "Mice with zinc deficiency were found to have a decreased number of insulin granules in their pancreatic β cells, as well as impaired glucose-stimulated insulin secretion (GSIS)." (PMID 29415457, 2018). "Significant changes in RNA expression of genes that regulate zinc homeostasis, response to oxidative stress and insulin production (including zip1, znt7, nrf2, ogg1, pax4, and insa) were found in zinc deficient, or zinc deficiency and arsenic exposed embryos." (PMID 28837703, 2017). "We also observed that zinc deficiency, and the combination of zinc deficiency and arsenic exposure, caused suppression of genes that regulate β cells development and insulin production in embryos." (PMID 28837703, 2017). "We also found that zinc deficiency, or zinc deficiency and arsenic exposure together, caused significant changes in expression of genes that regulate zinc homeostasis, response to oxidative stress and insulin production." (PMID 28837703, 2017). "We also evaluated the extent to which zinc deficiency and/or arsenic exposure altered the expression of key genes that regulate stress response and insulin production in the developing embryo." (PMID 28837703, 2017). "It has been reported that diet induced zinc deficiency impairs systemic insulin sensitivity, whereas acute zinc supplementation enhances insulin signaling and glucose deposition." (PMID 29057818, 2017). "Later in life, marginal maternal zinc deficiency in rats has been associated with decreased weight, increased percentage of body fat, and impaired insulin secretion in the offspring." (PMID 28837703, 2017). "Given this important possibility, we are currently testing the extent to which zinc deficiency and arsenic exposure disrupts insulin production in cultured pancreatic β cells." (PMID 28837703, 2017). "There is also a growing amount of literature linking zinc deficiency, and maternal zinc deficiency, to alterations in body composition, glucose tolerance, insulin response, and increased susceptibility to diabetic stress." (PMID 28837703, 2017). "Insulin activity and release from the pancreas is reduced in zinc deficiency, but insulin synthesis is normal." (PMID 26043030, 2015). "Taken together, these data suggest that the frequently present zinc deficiency in Thal patients is associated with decreased insulin secretion and reduced glucose disposal." (PMID 26043030, 2015). "Zinc deficiency may impair insulin synthesis and signaling, promote oxidative stress and inflammation, while excessive zinc intake may induce metabolic disturbances." (PMID 41439937, 2025). "In this context, the downregulation of Nox4 observed in zinc deficiency could promote depression of the insulin cascade." (PMID 38260166, 2023).
Zinc deficiency (continued). "Meanwhile, zinc deficiency intensified such adverse effects as: inflammation in the liver, disturbance in the urinary system, decreased growth, expression of genes responsible to oxidative stress and insulin production." (PMID 34678954, 2021). "The need for greater insulin mediated by zinc deficiency could be a driver towards eventual beta cell dysfunction." (PMID 26043030, 2015). "Therefore, zinc deficiency due to loss-of-function ZnT8 mutations shifts insulin oligomer equilibrium toward zinc-free monomers and dimers, which bind IAPP monomers more efficiently compared to zinc-bound hexamers." (PMID 25649462, 2015). "Thus, Zinc deficiency or alterations in ZnT8 expression have a potential to depress insulin secretion." (PMID 26244049, 2015). "Zinc deficiency may lead to impaired insulin synthesis and secretion, affecting glycemic control." (PMID 40248148, 2025). "In this study, zinc deficiency is a significant risk factor for exocrine and endocrine pancreatic dysfunction as zinc is involved in many of these processes within the pancreas, including glucagon secretion, digestive enzyme activity, and insulin packaging, secretion, and signaling." (PMID 34686155, 2021). "Few studies reported the effect of zinc deficiency on the endocrine pancreas, but its effect on exocrine pancreatic function had not been widely studied as low levels of zinc in the blood plasma affect the islets of Langerhans secretion and production of insulin." (PMID 34686155, 2021). "In the four in vivo studies, zinc deficiency intensified the adverse effect of exposure to iAs (inflammation in the liver, disturbance in the urinary system, decreased growth and influence on expression of genes responsible to oxidative stress and insulin production)." (PMID 34678954, 2021). "Modest, but significant effects of zinc deficiency and/or arsenic exposure were also found in developing embryos on the expression of genes that regulate zinc transport, response to oxidative stress, and insulin production (including zip1, znt7, nrf2, ogg1, pax4, and insa)." (PMID 28837703, 2017). "Therefore, zinc deficiency may induce abnormal insulin metabolism and oxidative stress." (PMID 27081400, 2016). "A fundamental question is what the effect of zinc-deficiency in β-cell granules is on the disease development, such as IAPP aggregation and IAPP-insulin interactions." (PMID 25649462, 2015). "Given the known roles that zinc deficiency plays in the physiology of insulin homeostasis and lipid metabolism, it is not surprising that several studies have reported positive effects of zinc supplementation on the risk of T2D and CVD." (PMID 32722790, 2021). "Rats with zinc deficiency have a reduced tolerance to glucose with no alteration in insulin production in response to glucose injection." (PMID 21513578, 2011).
abnormal glucose tolerance (28 papers, 2009 to 2026). "In conclusion, this study suggests that the majority of subjects with low fasting IGFBP-1 and adiponectin levels benefit from bariatric surgery with improved insulin sensitivity and glucose tolerance as well as reduced risk factors for cardiovascular disease and future abnormal glucose tolerance." (PMID 32934313, 2020). "Exosomes secreted from healthy islets have a protective role in the survival and function of the pancreas by increasing insulin content during abnormal glucose tolerance." (PMID 39619685, 2024). "In human subjects, circulating insulin levels positively correlated with serum sFRP2, and levels were higher in patients with abnormal glucose tolerance (34.2ng/ml) compared to controls (29.5ng/ml)." (PMID 27685706, 2016). "Previous study showed that the changes in insulin sensitivity from the time before conception through early pregnancy were inversely correlated with the changes in maternal weight gain in lean women with normal and abnormal glucose tolerance." (PMID 33732212, 2021). "Furthermore, we determined that BMI, glucose and insulin concentrations, IR, FAI and levels of TG and HDL-c are important risk factors for abnormal glucose tolerance in women with PCOS and these results confirm the previous reports." (PMID 33092301, 2020). "Furthermore, the insulin sensitivity of the overweight/obese group significantly increased following exercise training even in patients with abnormal glucose tolerance at baseline (i.e., the IGT group)." (PMID 29471797, 2018). "Unlike previous studies from a clinical setting, we measured circulating sFRP2 levels in serum from humans across a range of BMI and with normal and abnormal glucose tolerance and showed a positive correlation with serum insulin, triglyceride, HOMA%B and HOMAIR." (PMID 27685706, 2016). "In patients with abnormal glucose tolerance due to impaired Si, successful pituitary surgery restores normoglycemia in those with preserved beta cell function but not in those with abnormal insulin secretion." (PMID 31620090, 2019).
alcohol abuse (28 papers, 2004 to 2026). The use of alcoholic beverages to excess, either on individual occasions ("binge drinking") or as a regular practice. "Precipitating factors such as infections, alcohol abuse, and insulin dose omission were the remaining main causes of DKA in diagnosed T1DM." (PMID 31722517, 2020). "Hence, it is possible alcohol abuse causes insulin resistance in skeletal muscle by disrupting lipid homeostasis in adipose tissues." (PMID 32760285, 2020). "who examined the crosstalk of chronic alcohol abuse and both the insulin/IGF and Wnt pathways on liver regeneration." (PMID 35663960, 2022). "In adults with T2D, a smoking history, alcohol abuse, and insulin treatment were related to DFU." (PMID 38403299, 2024). "Since previous studies have shown that alcohol abuse decrease mTOR pathway, insulin signaling factors and various enzymes for glucose uptake and fatty acid oxidation could be reduced in skeletal muscle." (PMID 32760285, 2020). "Although stellate cell activation and fibrogenesis are known consequences of chronic alcohol abuse in humans, our results link genetic factors and ethanol-mediated insulin/IGF-1 resistance to severity of steatohepatitis and proneness to develop progressive alcoholic liver disease." (PMID 20814553, 2010). "In one Finnish study, basal insulin levels were equivalent to or better than the commonly used Psychopathy Checklist Revised (PCL-R) as a predictor of recidivism in adults with a history of violent crime and alcohol use disorder." (PMID 41441197, 2025). "Neither alcohol abuse, insulin treatment, chemotherapy, antacids, nor diuretics were related to 30-day mortality (0% [p = 1.0], 6.1% [p = 0.774], 8.3% [p = 0.484], 5.5% [p = 0.926], 6.8% [p = 0.334], respectively)." (PMID 39408254, 2024). "However, from the standpoint of therapeutics, a parsimonious approach that globally supports insulin/IGF-1 pathways in the human brain could potentially provide optimum neuroprotection for both neurons and oligodendrocytes in the context of alcohol use disorders." (PMID 29204305, 2017).
autoimmune thyroid disease (28 papers, 2010 to 2026). Inflammatory disease of the thyroid gland due to autoimmune responses leading to lymphocytic infiltration of the gland. "Selenium can also modulate the immune response in patients with autoimmune thyroiditis and retains insulin-mimetic properties, an effect likely determined by the stimulation of tyrosine kinases involved in the insulin signaling pathway." (PMID 35682497, 2022). "The obtained results indicate that thyroid autoimmunity is, apart from vitamin D status, insulin sensitivity and sex hormones, regulated by many other factors (such as genetic factors, iodine and selenium intake, age, infections, radiation exposure and endocrine disruptors)." (PMID 34106452, 2021). "These include exposure to ionizing radiation, iodine deficiency auto immune thyroiditis and long-standing multi nodular goitres (MNG), while there are other risk factors which are less clear including diet, body weight, insulin resistance and exposure to environmental pollutants." (PMID 29415672, 2018). "Several were initially treated as T2DM and later required insulin, underscoring the T2DM-like onset with coexisting thyroid autoimmunity seen in our patient." (PMID 41024896, 2025). "We evaluated the prevalence of glutamic acid decarboxylase (GADA) and tyrosine phosphatase-protein antibodies (IA2A), their titers and their relation to first phase insulin response (FPIR) and glucose tolerance in autoimmune thyroid diseases (ATDs) patients." (PMID 28724056, 2017). "Consistent with this theory, four other insulin-treated diabetic patients with herpes zoster, two of whom with significant thyroid autoimmunity, never exhibited LIL." (PMID 24961832, 2014).
breast tumor (28 papers, 1978 to 2025). "We next computed signature scores of gene sets associated with the insulin/PI3K pathway in ER+/HER2− breast tumors in METABRIC." (PMID 33127913, 2020). "The anti-tumorigenic properties of MET have been reported in several studies associated with indirect action (reduced insulin levels) or direct actions on molecular pathways that regulate breast tumor cell growth and death." (PMID 33108409, 2020). "Most human breast tumors have mutations that elevate signaling through a key metabolic pathway that is induced by insulin and a number of growth factors." (PMID 21646685, 2011). "Insulin has a paracrine effect on secretion of adipokines, which may contribute to the increasing risk of more aggressive breast tumors." (PMID 25916213, 2016). "The gene ontology studies of these genes also revealed enrichment of these genes in the insulin signaling pathway, suggesting a link of this pathway in cell proliferation of breast tumors." (PMID 33593445, 2021). "Heuson and Legros, while administering glucose and insulin to rats with a breast tumor, observed a greater increase in tumor mass compared to the control group, especially under the influence of insulin." (PMID 33562380, 2021). "We observed an association between insulin treatment and increased p-mTOR and IGF1R expression of breast tumors, especially in premenopausal women." (PMID 29486734, 2018). "In particular, the phosphatidylinositol-3 kinase (PI3K)/AKT pathway is a critical component of the insulin responses, promoting breast tumor cell growth, survival and aggressive behaviour." (PMID 28038446, 2017). "The epidemiological studies investigated the incidence of primary breast tumours upon insulin treatment in DM patients." (PMID 26242987, 2015). "The insulin signaling pathway influences breast tumor growth, proliferation, transformation and survival." (PMID 17883861, 2007). "Insulin has long been proposed to be involved in breast tumor progression." (PMID 31315653, 2019). "Higher insulin levels may give the tumor a growth advantage, as most breast tumors express the IGF-1R and IR-A, both of which are involved in proliferation and tumorigenesis and are associated with tumor progression." (PMID 31455425, 2019). "Any insulin use was significantly associated with higher expression of IGF1R (OR = 2.36; 95%CI:1.02–5.52; p = 0.04) and p-mTOR (OR = 2.35; 95%CI:1.13–4.88; p = 0.02) in breast tumors." (PMID 29486734, 2018). "In agreement, heparanase enhances insulin-induced proliferation of breast tumor cells in vitro." (PMID 28038446, 2017). "In turn, adipokines alter AMPK activity and might play a crucial role in adipokine-altered insulin sensitivity and breast tumour cell growth." (PMID 21774820, 2011). "In turn, some adipokines might activate AMPK and increase insulin sensitivity and inhibits breast tumor development." (PMID 21774820, 2011). "The insulin/IGF system and estrogens act synergistically as potent mitogens in normal breast as well as in breast tumor cells." (PMID 25798130, 2015). "The mock factors, which were generated from an insulin/muscle-biopsy gene expression dataset (GSE 7146), were unable to distinguish between samples based on breast tumor status in the independent validation set." (PMID 21781289, 2011). "Further, the ability of dapagliflozin to enhance the efficacy of chemotherapy correlates with its effect to reduce circulating insulin in some but not all breast tumors." (PMID 35595952, 2022). "At the cellular level, insulin as well as IGF-1 dramatically synergizes with GPCR agonists in inducing mitogenic signaling in multiple solid tumors including pancreas, colon, prostate, and breast tumors." (PMID 25798130, 2015). "Insulin and insulin-like growth factor-1 (IGF-1) are the most important negative regulators of the sex hormone-binding globulin (SHBG) synthesis pathway in vitro and may lead to the development of breast tumors in a variety of ways." (PMID 35464024, 2022).